HOTAIR (HOX transcript antisense RNA)
Diseases named in the same sentence as HOTAIR in open-access papers (continued):
Sharing a sentence is not in itself a finding about the gene and the disease.
gastric cancer (continued). "Studies had found that HOTAIR could interact with PRC2 to trimethylate H3K27, which could reduce the expression of E-cadherin in gastric cancer." (PMID 37576402, 2023). "Furthermore, HOTAIR was identified as an unfavorable prognostic factor for overall survival (OS) in the esophageal carcinoma (ESCA) and gastric cancer (GC), as the HR were 1.94 and 1.58, respectively." (PMID 36924407, 2023). "In addition, HOTAIR activates the PI3K/AKT/MRP1 signaling pathway by targeting miR-126, to promote DDP resistance in gastric cancer." (PMID 35227173, 2022). "Even though, there is no direct evidence showing that HOTAIR and HTTAS relate to gastric cancer so far, some studies found that HOTAIR has stable expression in peripheral blood and can be used as a non-invasive diagnostic marker for gastric cancer." (PMID 36338997, 2022). "Moreover, knockdown of HOTAIR inhibited expression of the multidrug-resistance genes ABCB1, ABCC1, and ABCG2 in cisplatin-resistant gastric cancer cells and reduced xenograft tumor growth in nude mice." (PMID 36471329, 2022). "Silencing HOTAIR reduces invasiveness and reverses EMT in gastric cancer cells." (PMID 34405017, 2021). "In conclusion, HOTAIR’s positive regulation of CCND1 and CCND2 in gastric cancer may be realized by reverse regulation of miRNA‐206." (PMID 33473276, 2021). "Studies have found that HOTAIR and its combination with PRC2 inhibited the expression of miR34a, which controls the target genes C-Met (HGF/C-Met/Snail pathway) and Snail, thereby helping gastric cancer cells to develop EMT and promote tumor metastasis." (PMID 34422902, 2021). "In addition, lncRNAs PVT1, HOTAIR and CASC9 also promoted PTX resistance of gastric cancer through modulating expression of various genes." (PMID 32192494, 2020). "Additionally, a recent study showed that HOTAIR controls Rab22a expression in ovarian cancer by sponging miR-373 and regulates HER2 expression in gastric cancer by sponging miR-331-3p." (PMID 33302562, 2020). "For example, HOTAIR promotes osteosarcoma development by sponging miR-217 and targeting ZEB1, HOTAIR faciliates gastric cancer progression via miR-217-GPC5 axis, and HOTAIR regulates the development of non-small cell lung cancer through miR-217/DACH1 signaling pathway." (PMID 32700738, 2020). "For example, HOTAIR activates the PI3K/Akt pathway by inhibiting the expression of miR-126 and promotes the development of cisplatin resistance in gastric cancer, while HOTAIR decreases chemoresistance through the activation of Wnt/β-catenin signaling in ovarian cancer." (PMID 29416704, 2018). "In a manner similar to that observed for HOTAIR, UCA1 has also been shown to regulate miRNAs (in this instance miR-27b) as part of a multi-drug resistance to various chemotherapies (including cisplatin) in gastric cancer." (PMID 28430163, 2017). "HOTAIR exerts its effects by functioning as a sponge on miR-331-3p and subsequently blocking miR-331-3p-mediated suppression on its target gene HER2, a well-known regulator of gastric cancer." (PMID 26978351, 2016). "Moreover, HOTAIR can act as a sponge for endogenous miR-331-3p, preventing the silencing of human epithelial growth factor receptor 2 (HER2) oncogene in gastric cancer." (PMID 26379360, 2015). "In gastric cancer cells, the EMT may be triggered by HOTAIR through up-regulation of “snail” (a transcription factor involved in EMT)." (PMID 25334066, 2014). "Considering the interaction of HOTAIR/miR-331-3p, we therefore hypothesize that HOTAIR may also regulate HER2 expression in gastric cancer, which signifies the role of HOTAIR in the tumorigenesis-regulating network." (PMID 24775712, 2014). "Bivariate correlation analysis showed that expression of HER2 was significantly correlated with HOTAIR transcript level in gastric cancer tissues compared with normal counterparts." (PMID 24775712, 2014).
gastric cancer (continued). "In this study, we tested the expression of HOTAIR in gastric carcinoma samples and their surrounding non-tumorous tissues." (PMID 24775712, 2014). "The expression of HOTAIR was significantly higher in cancer lesions than in adjacent non-cancerous tissues in human gastric cancers." (PMID 24130837, 2013). "The results of the MTT assay demonstrated that neither up-regulation nor down-regulation of HOTAIR affected gastric cancer cell proliferation." (PMID 24130837, 2013). "We further analyzed in gastric cancer subtypes the expression of genes involved in epigenetic controls, such as EZH2 (Enhancer of zest homolog 2 involved in histone modifications), non-coding RNA (including long non-coding RNAs such as HOTAIR, H19) and DNMT1 (involved in DNA methylation)." (PMID 40868070, 2025). "In addition, HOTAIR could combine with miR‐331‐3p in a sponge‐like form and function as the competing endogenous RNA to regulate HER2 expression in gastric cancer cells." (PMID 33473276, 2021). "HOTAIR has further been found to target miR-34a and activate the PI3K/AKT pathway, consequently decreasing the expression of caspase-3 and BAX, increasing the expression of BCL-2, inhibiting apoptosis, and inducing DDP resistance in gastric cancer cells in vitro and in vivo." (PMID 32460771, 2020). "HOTAIR might act as competing endogenous RNA and interact with microRNA (miRNA), such as miR-331-3p and miR-152, to regulate human epidermal growth factor receptor 2 (HER2) and human leukocyte antigen-G (HLA-G) expression in gastric cancer cells." (PMID 32509569, 2020). "More than that, after excluding the influence of other parameters, higher HOTAIR expression, higher miR‐17‐5p expression, poor differentiation, advanced AJCC stage (III + IV) and presence of lymph node metastasis appeared as predictors for gastric cancer patients’ poor prognosis (P < 0.05)." (PMID 30338929, 2019). "In addition, HOTAIR was also found to directly target miR‐17‐5p, and PTEN appeared to be subject to the modification of HOTAIR and miR‐17‐5p in its acting on the viability, proliferation, EMT process, and apoptosis of gastric cancer cells." (PMID 30338929, 2019). "The HOTAIR/miR‐17‐5p/PTEN axis could be regarded as the potential treatment targets for gastric cancer, and adjuvant therapy of SQFZ injection could assist in further improving the treatment efficacy of chemo‐therapies for gastric cancer." (PMID 30338929, 2019). "The co-ordination of HOTAIR and PRC2 down-regulates miR-34a expression and activates miR34a target genes, such C-Met (HGF/C-Met/Snail pathway) and Snail, which are central players in the epithelial-mesenchymal transition (EMT) in advanced stages of gastric cancer." (PMID 29721215, 2018). "However, the significance of HOTAIR expression in gastric cancer tissues from clinic has not been fully studied." (PMID 27751178, 2016). "For instance, HOTAIR, a well-known lncRNA could inhibit the expression of FGF1 by regulating miR-326 in human glioma, and also functioned as a competing endogenous RNA to regulate HER2 expression by sponging miR-331-3p in promoting gastric cancer." (PMID 27267902, 2016). "HOTAIR expression is higher in gastric cancer tissues than corresponding noncancerous tissues." (PMID 27686732, 2016). "Indeed, HOTAIR, HULC and H19 expression levels in plasma have been demonstrated to correlate with outcome in series of patients with metastatic colon cancer, hepatocellular carcinoma and gastric cancer, respectively." (PMID 27340923, 2016). "Furthermore, we verified that HOTAIR was located both in the nucleus and cytoplasm of gastric cancer cells, and RNA immunoprecipitation (RIP) assays showed that HOTAIR could bind to PRC2." (PMID 26136075, 2015). "In addition, HOTAIR also epigenetically downregulates miR34a by binding to PRC2 to activate its target genes C-Met (HGF/C-Met/Snail pathway) and Snail, thereby promoting EMT in advanced stages of gastric cancer." (PMID 26136075, 2015).
gastric cancer (continued). "The ceRNA regulatory network involving HOTAIR and the positive interaction between HOTAIR and HER2 may contribute to a better understanding of gastric cancer pathogenesis and facilitate the development of lncRNA-directed diagnostics and therapeutics against this disease." (PMID 24775712, 2014). "In addition, studies have shown that inhibition of HOTAIR expression in gastric cancer cells decreases the expression of matrix metalloproteinases 1 and 3, reduces the invasive capability of cancer cells, and reverses the epithelial–mesenchymal transition (EMT) in gastric cancer cells." (PMID 27464701, 2016). "Thus, the expression of HOTAIR was seemed to be an independent predictor of overall survival.The role of lncRNA CHRF promotes cell invasion and migration through EMT, which may provide a potential target for the biological diagnosis and therapy of gastric cancer." (PMID 34422902, 2021). "Finally, our experimental data suggest that targeting the HOTAIR/HER2 interaction may represent a novel therapeutic application, thus contributing to better knowledge of the efficacy and tolerance of trastuzumab-based therapy in HER2-positive gastric cancer patients." (PMID 24775712, 2014).
lung cancer (106 papers, 2013 to 2025). A malignant neoplasm involving the lung. "An illustrative example is HOTAIR, which has been implicated in epigenetic modifications associated with lung cancer progression." (PMID 39201688, 2024). "For instance, HOTAIR is highly expressed in lung epithelial cells and has been implicated in lung cancer progression by modulating chromatin states and gene expression." (PMID 39201688, 2024). "Meanwhile, studies focusing on the gene polymorphism of HOTAIR and the value of tumor prognosis and diagnosis, such as lung cancer, have also been published." (PMID 36924407, 2023). "High expression of HOTAIR has also been associated with increased chemoresistance and lower survival rates in lung cancer patients." (PMID 36869839, 2023). "According to previous research studies, the malignancies associated with the polymorphism of HOTAIR include lung cancer, oral cancer, and urothelial cell carcinoma." (PMID 36361470, 2022). "Although, HOTAIR rs920778 and rs1899663 significantly increase susceptibility to lung cancer, the roles of HOTAIR SNPs in lung cancer still need to be further studied." (PMID 32394637, 2020). "In order to investigate the relationship between the HOTAIR SNPs (rs920778, rs1899663, and rs4759314) and the susceptibility to lung cancer, we analyzed DNA from 196 cases of patients with NSCLC and 196 healthy controls." (PMID 32394637, 2020). "The relationship between SNPs in rs920778, rs1899663, and rs4759314 loci of the HOTAIR gene and susceptibility to lung cancer was analyzed from a genetics perspective." (PMID 32394637, 2020). "In order to explore the potential of HOTAIR as a diagnostic marker for lung cancer, we firstly investigated the expression of HOTAIR in different tumors using online Gene Expression Profiling Interactive Analysis (GEPIA) resources." (PMID 32394637, 2020). "Subsequently, the relationship between HOTAIR gene SNPs (rs920778, rs1899663, and rs4759314) and susceptibility to lung cancer was investigated." (PMID 32394637, 2020). "Circulating HOTAIR has been detected in lung cancer plasma, and it appears to be associated with clinical-pathological features of the patients." (PMID 32397382, 2020). "In lung cancer, the frequently reported cancer-associated lncRNAs include HOTAIR, H19, MALAT1, ANRIL, and GAS5." (PMID 31889956, 2019). "Several known lung cancer-associated lncRNAs, such as HOTAIR, GAS5, PVT1, and UCA1 were found in this top list which further supported the power of this analysis." (PMID 26862852, 2016). "Of note, Kaplan-Meier plotter performed on a cohort of these lung cancers showed that lower expression of HOTAIR linked with overall survival in all lung cancer, and ADCs, but not in lung SCCs." (PMID 26658322, 2015). "Materialization of HOTAIR’s clinical potential requires further investigation of the molecular mechanisms underlying the tumor-promoting actions of HOTAIR in lung cancer." (PMID 25491133, 2014). "Here we review the molecular mechanisms underlying HOTAIR-mediated aggressive phenotypes of lung cancer." (PMID 25491133, 2014). "Herein we review the literature of HOTAIR in lung cancer with an emphasis on the molecular mechanisms underlying its regulation of lung cancer." (PMID 25491133, 2014). "The enhanced expression of HOTAIR is associated with invasiveness, metastasis and poor prognosis in a variety of cancers such as breast, colon, pancreatic and lung cancer." (PMID 24130837, 2013). "CCL-5 upregulates HOTAIR in lung cancer, causing cisplatin resistance." (PMID 39717771, 2024). "The results demonstrated that CCDC26 and IFNG-AS1 may be new biomarkers for lung cancer, SNHG3 may be associated with PDL1 for lung cancer, and HOTAIR and BDNF-AS may be potential biomarkers for neuroblastoma." (PMID 37655066, 2023). "Likewise, HOTAIR upregulation was associated with drug resistance by Wnt/β-catenin pathway activation in lung cancer, and colorectal cancer." (PMID 34778043, 2021).
lung cancer (continued). "Furthermore, HOTAIR has been reported to be associated with drug sensitivity in many cancers, such as lung cancer and ovarian cancer." (PMID 33824300, 2021). "Upregulation of lncRNA HOTAIR in lung cancers has been linked to lymph node metastasis." (PMID 33803619, 2021). "Therefore, we further explored the relationship between the HOTAIR gene SNPs (rs920778, rs1899663, and rs4759314) and the susceptibility to patients with lung cancer." (PMID 32394637, 2020). "Besides, both H19 and HOTAIR were identified as non-invasive diagnostic biomarkers in the sputum of lung cancer patients." (PMID 32438606, 2020). "The high expression of HOTAIR is associated with metastasis and the poor prognosis of lung cancer." (PMID 31889956, 2019). "HOTAIR has emerged as a promising diagnostic and therapeutic target for lung cancer." (PMID 25491133, 2014). "It remains unknown whether elevated expression of HOTAIR in lung cancer is caused by genetic alterations, such as amplification, deletion, or point mutations." (PMID 25491133, 2014). "Research on lncRNAs in lung cancer is also receiving increasing attention, with many lncRNAs such as MALAT1 and HOTAIR being abnormally expressed in lung cancer tissues." (PMID 41394878, 2025). "In PC9 lung cancer cells, overexpression of HOTAIR enhances H3K27me3 recruitment to p16 and p21 promoters." (PMID 39940704, 2025). "Within lung cancer pathology, certain lncRNAs, such as MALAT1 and HOTAIR, are significantly associated with the onset and progression of the disease." (PMID 41394878, 2025). "In nonsmall cell lung cancer, HOTAIR promotes cell growth, invasion, and migration by sponging miR-149-5p." (PMID 40686703, 2025). "Conversely, HOTAIR interacts with chromatin modification complexes to modify chromatin states, which subsequently affects gene expression and promotes metastasis in lung cancer." (PMID 41394878, 2025). "In lung cancer, HOTAIR promotes tumor occurrence and development by regulating the expression of genes related to cell proliferation, apoptosis, and metastasis." (PMID 41394878, 2025). "HOTAIR is a lncRNA with key roles in lung cancer, including resistance to cisplatin in LUAD cells, cell cycle control, metastasis and others." (PMID 41373437, 2025). "Increased expression of HOTAIR is found in tumor tissues of patients and is associated with LNM in patients with lung cancer." (PMID 39725668, 2024). "Deregulation of HOTAIR lncRNA expression can be a biomarker of poor prognosis and cancer progression for several solid tumors such as ovarian, gastric, and lung cancer." (PMID 38157198, 2024). "In lung cancer, HOTAIR promotes tumor invasion, metastasis, and angiogenesis by modulating chromatin remodeling complexes, transcription factors, and signaling pathways involved in tumor progression." (PMID 39201688, 2024). "The expression of HOTAIR regulates proliferation, survival, invasion, metastasis, and drug resistance in lung cancer cells." (PMID 39725668, 2024). "Key lncRNAs such as NEAT1, TUG1, MALAT1, HOTAIR, and GAS5 demonstrate a crucial role in lung cancer progression and serve as powerful prognostic and diagnostic biomarkers." (PMID 39201688, 2024). "HOTAIR: HOTAIR is a well-characterized lncRNA implicated in COPD and lung cancer pathogenesis, whose dysregulated expression correlates with disease severity and progression." (PMID 39201688, 2024). "Li and colleagues also found that HOTAIR expression is increased in gefitinib-resistant lung cancer tissues and that its overexpression can lead to enhanced drug resistance in lung cancer cell models." (PMID 38887279, 2024). "Silencing of EZH2 sensitized the lung cancer cells to gefitinib and induced expression of p16 and p21, suggesting that HOTAIR contributes to gefitinib resistance by regulating EZH2/p16/p21 axis." (PMID 38887279, 2024).